RNU4-23P (RNA, U4 small nuclear 23, pseudogene)
Gene: Small nuclear RNA gene on chromosome 11 (122,927,034 to 122,927,173, forward strand). Ensembl gene ENSG00000199709.
Homologues: Orthologues: chimpanzee U4 (99% identical), macaque U4 (90% identical), pig U4 (81% identical), mouse Gm25104 (63% identical), dog U4 (52% identical), dog U4 (51% identical), guinea pig U4 (51% identical), dog U4 (48% identical), guinea pig U4 (47% identical). Paralogues in human: RNU4-13P (86% identical), RNU4-67P (84% identical), RNU4-76P (84% identical), RNU4-44P (84% identical), RNU4-7P (84% identical), RNU4-58P (83% identical), RNU4-35P (82% identical), RNU4-45P (80% identical), RNU4-68P (80% identical), RNU4-80P (79% identical), RNU4-8P (79% identical), RNU4-84P (79% identical), and 81 more.